LPL (lipoprotein lipase)
Diseases named in the same sentence as LPL in open-access papers (continued):
Sharing a sentence is not in itself a finding about the gene and the disease.
familial chylomicronemia syndrome (continued). "It is indicated for treating familial chylomicronemia syndrome (FCS), a rare inherited disorder often caused by mutations in the lipoprotein lipase (LPL) gene." (PMID 40874255, 2025). "The monogenic form of the disease, known as familial chylomicronemia syndrome (FCS), is rare and primarily caused by mutations in LPL, impairing the clearance of triglyceride-rich lipoproteins (TRLs)." (PMID 40142634, 2025). "Distinguishing between patients with familial chylomicronemia syndrome or with multifactorial chylomicronemia is important as recent specific therapy for lipoprotein lipase (LPL) genetic deficit is available." (PMID 37529514, 2023). "An antisense oligonucleotide (ASO) to APOC3 (volanesorsen) very effectively lowered TG levels in patients with familial chylomicronemia syndrome (FCS), including those with LPL-null mutations." (PMID 34981790, 2022). "Previous studies have shown that familial chylomicronemia syndrome, in most cases, is a result of a genetic-related alterations in LPL function." (PMID 35144640, 2022). "APOC2 is the obligate activator of LPL, and APOC2 deficiency leads to familial chylomicronemia syndrome." (PMID 34981790, 2022). "This includes familial chylomicronemia syndrome (FCS), a condition caused by mutations in the lipoprotein lipase (LPL) gene or other genes that regulate the function of this enzyme (i.e APOC2 and the LMF1 (lipase maturation factor 1))." (PMID 33588820, 2021). "When due to very rare monogenic mutations in the genes encoding the enzyme, lipoprotein lipase, or its regulators, APOC2, APOA5, GPIHBP1, and LMF1, it is referred to as the familial chylomicronemia syndrome." (PMID 33193106, 2020). "Familial chylomicronemia syndrome (FCS) is an autosomal recessive disorderthat affects approximately 1 to 10 individuals per million and is caused byvariants in the genes encoding for the lipoprotein lipase (LPL) enzyme." (PMID 41026863, 2025). "Familial chylomicronemia syndrome (FCS) is a rare disorder of triglyceride (TG) metabolism caused by loss of function variants in one of five known canonical genes involved in chylomicron lipolysis and clearance—LPL, APOC2, APOA5, LMF1, and GPIHBP1." (PMID 38974610, 2024). "For instance, rs132642 in APOL3 had no annotation in ClinVar, and rs328 in LPL is annotated as benign in the phenotype hyperlipoproteinemia type I. This mutation truncates the last two codons of the protein." (PMID 37065472, 2023). "The APPROACH trial was a randomized double-blinded placebo-controlled trial that enrolled 66 patients with familial chylomicronemia syndrome (FCS), a rare genetic disease caused by an inactivating mutation of both alleles of LPL genes and genes encoding other proteins required for LPL activity." (PMID 34440189, 2021). "In fact, subjects with familial chylomicronemia syndrome, which is due to pathogenic mutations in genes controlling LPL itself or LPL activity, do not usually exhibit an elevated risk of atherosclerotic CVD despite the very high levels of TGs." (PMID 32849290, 2020). "Polymorphisms in the LPL gene that encode non-functioning LPL proteins lead to LPL deficiency, also known as familial chylomicronemia syndrome (FCS)." (PMID 33172164, 2020). "Bi-allelic pathogenic mutations in LPL, APOC2, GPIHBP1, APOA5, or LMF1, that lead to reduced LPL action, are used to confirm familial chylomicronemia syndrome, a rare autosomal recessive disorder characterized by severe elevation of TG levels, eruptive cutaneous xanthomas and acute pancreatitis." (PMID 32849290, 2020). "The familial chylomicronemia syndrome (FCS) patients, who have deficiency in APOC2 or LPL, consuming normal diet develop severe hypertriglyceridemia and chylomicronemia and often manifest eruptive xanthomas, lipemia retinalis, and acute and recurrent pancreatitis." (PMID 28107429, 2017).
familial chylomicronemia syndrome (continued). "Unlike familial chylomicronemia syndrome, which is caused by genetic deficiency of LPL and characterized by severe HTG but very low LDL-C, mice with P407 injection have elevated LDL-C, suggesting that P407 may have actions additional to LPL inhibition." (PMID 35681489, 2022). "Furthermore, three patients had variants linked to familial chylomicronemia syndrome: one was compound heterozygous for two likely pathogenic variants in LPL, another was homozygous for a likely pathogenic variant in LMF1, and the third was heterozygous for a likely pathogenic variant in LPL." (PMID 40806502, 2025). "The role of ApoC-III in LPL-independent pathways is demonstrated in familial chylomicronemia syndrome (FCS) patients lacking LPL or LPL activity." (PMID 38429638, 2024).
type 2 diabetes (65 papers, 2005 to 2025). "Meta-analysis of human studies demonstrated that LPL modulation was associated with significant improvements in the lipid profile of patients with type 2 diabetes, including reductions in triglycerides and LDL-C, and an increase in HDL-C." (PMID 41373652, 2025). "Increased frequencies of the carriers of the LPL rs264 A allele were observed among the patients with type 2 diabetes." (PMID 38392646, 2024). "To date, a number of studies have examined the association between various LPL gene polymorphisms and lipid metabolism parameters, type 2 diabetes and coronary artery disease." (PMID 38392646, 2024). "Increased frequencies of the carriers of the LPL rs264 A allele were found among the patients with type 2 diabetes." (PMID 38392646, 2024). "Lipid-lowering LPL variants were associated with decreased risks of hypertension, type 2 diabetes, nonalcoholic fatty liver disease, and bladder cancer (q<0.05)." (PMID 38127052, 2023). "The T-allele of this SNP was associated with increased LPL in EpiHealth (β 1.9, SE 0.17, p = 2.2 × 10−29) and provided a causal estimate of OR 0.970 (0.922, 1.020) for type 2 diabetes." (PMID 31446444, 2019). "Triglyceride-lowering alleles in the LPL pathway are associated with lower risk of coronary disease and type 2 diabetes independently of LDL-C–lowering genetic mechanisms." (PMID 30326043, 2018). "The strong and consistent association of multiple independent LPL alleles with lower risk of type 2 diabetes found in our study extends and reinforces previous reports by us and others limited to the rs180117712 and rs32812,14,15 alleles." (PMID 30326043, 2018). "Specifically, a gain-of-function variant of LPL was associated with higher insulin sensitivity, lower fasting glucose and a lower risk of type 2 diabetes." (PMID 29502266, 2018). "This study aimed to evaluate the postprandial lipid metabolism after the ingestion of a liquid high-fat meal in type 2 diabetic patients with abdominal obesity, and determine if the PvuII polymorphisms of LPL influence their postprandial lipid responses." (PMID 28814963, 2017). "It has been indicated that the LPL gene polymorphism may influence lipid metabolism parameters and may also be a risk factor for type 2 diabetes and coronary artery disease." (PMID 38392646, 2024). "Lipoprotein lipase (LPL)-related single nucleotide polymorphism (SNP) rs285 C was identified to be significantly associated with higher risk of rapid decline in kidney function in type 2 diabetic patients." (PMID 39258389, 2024). "Triglyceride-lowering LPL alleles were also associated with protection against type 2 diabetes." (PMID 30326043, 2018). "Whether the association of genetic variants that inactivate ANGPTL4 with reduced type 2 diabetes risk is mediated exclusively via modulation of lipoprotein lipase activity or involves other mechanisms remains to be clarified." (PMID 29899519, 2018). "Conversely, a loss-of-function variant of LPL was associated with higher risk of type 2 diabetes." (PMID 29502266, 2018). "In this study, we assess the postprandial lipid responses after a high-fat challenge in type 2 diabetic patients with abdominal obesity, and determine whether the PvuII polymorphisms of LPL influence their postprandial lipid metabolism." (PMID 28814963, 2017). "The relative insulin deficiency that occurs in type 2 diabetes impairs the action of lipoprotein lipase and results in lower HDL-C levels and higher TG levels, which may improve with improved glycemic control." (PMID 29083371, 2016). "Therefore, the aims of this study were to evaluate the postprandial lipid responses after the ingestion of a liquid high-fat meal in type 2 diabetic patients with abdominal obesity, and determine if the PvuII polymorphisms of LPL influence their postprandial lipid metabolism." (PMID 28814963, 2017). "We conducted a systematic review on cardiac metabolomic alterations in type 2 diabetes and the interplay with lipoprotein lipase (LPL)." (PMID 41373652, 2025).
type 2 diabetes (continued). "LPL, the key enzyme in triglyceride metabolism, potentially accelerates renal function decline in type 2 diabetes patients." (PMID 41438111, 2025). "Ultimately, 11 studies met all inclusion criteria and were included in the final analysis, providing robust evidence on the relationship between LPL activity and cardiac metabolomics in type 2 diabetes." (PMID 41373652, 2025). "This review systematically examines the role of LPL in metabolic dysfunction and cardiac outcomes in individuals with type 2 diabetes." (PMID 41373652, 2025). "One example is genetic variants in the lipoprotein lipase gene (LPL) that reduce TAG levels, which are associated with a lower risk of CVD and type 2 diabetes (T2D)." (PMID 41002985, 2025). "In patients with type 2 diabetes, both lipoprotein lipase production and circulating lipoprotein lipase levels are reduced." (PMID 41155203, 2025). "This is a common phenomenon among people with type 2 diabetes due to the decreased activity of lipoprotein lipase (LPL), whose major role is to break down blood triacylglycerols." (PMID 38398503, 2024). "LPL activity increased peripheral lipolysis of triglycerides and led to lower CVD and type 2 diabetes risk." (PMID 39286650, 2024). "In addition, the LPL rs264 polymorphism may be associated with a risk of type 2 diabetes." (PMID 38392646, 2024). "Decreased LPL, for instance, leads to increased plasma TG concentrations in patients with type 2 diabetes." (PMID 38973609, 2024). "In patients with type 2 diabetes, the elevated serum triglyceride levels negatively correlate with circulating LPL levels, and positively with circulating APOC1, APOC3, ANGPTL3, ANGPTL4 and ANGPTL8 levels." (PMID 37448184, 2023). "Both APOC1 and APOC3 inhibit LPL activation, and the circulation levels are investigated in patients with type 2 diabetes." (PMID 37448184, 2023). "But there are currently no reports on the effect of this novel GKA, dorzagliatin, on lipoprotein lipase, hepatic triglyceride content, and hepatic triglyceride synthesis in type 2 diabetes patients." (PMID 38179187, 2023). "ANGPTL 3, 4 and 8 inhibit the activity of LPL, and their circulating levels in the patients with type 2 diabetes have been reported." (PMID 37448184, 2023). "LPL mass was lower in patients with type 2 diabetes compared with individuals with normal glucose tolerance." (PMID 37448184, 2023). "ApoC-II is an activator of lipoprotein lipase and increased levels of total apoC-II appear in patients with type 2 diabetes." (PMID 36080270, 2022). "Because modulation of LPL activity in oxidative tissues affects free fatty acid delivery, and thereby nutrient partitioning and insulin sensitivity, endogenous regulators of LPL activity may impact glucose homeostasis and risk for development of type 2 diabetes." (PMID 29899519, 2018). "Another study found that gain-of-function alleles of LPL and loss-of-function alleles of ANGPTL4 were associated with lower risk of type 2 diabetes." (PMID 29502266, 2018). "In addition, increased plasma levels of ApoC-III (an inhibitor of LPL) could also contribute to the decreased catabolism of VLDL in patients with type 2 diabetes, since increased plasma levels of ApoC-III were associated with impaired VLDL clearance in obese insulin-resistant men." (PMID 25725623, 2015). "The activity of LPL, the enzyme responsible for chylomicron hydrolysis, is significantly reduced in patients with type 2 diabetes." (PMID 25725623, 2015). "This defect in VLDL catabolism mainly reflects the reduced activity of LPL in type 2 diabetes, particularly in adipose tissue." (PMID 25725623, 2015). "Based on the present findings and previous reports, RBP4 is thought to increase RLP-TG through the activation of RXR, inducing the overexpression of apoC-III and decreasing LPL activity in type 2 diabetic patients." (PMID 23671852, 2013). "Given that LPL is a key enzyme in lipid metabolism, it is considered the main candidate gene for type 2 diabetes." (PMID 24086538, 2013).
type 2 diabetes (continued). "In type 2 diabetes the triglyceride level is increased, which is due to multiple factors related to insulin and carbohydrate metabolism, LPL activity, CETP activity..." (PMID 15636639, 2005). "Low levels of muscle lipoprotein lipase in individuals that are obese or have a metabolic condition, such as type 2 diabetes, may influence high responses in PHTG." (PMID 38021207, 2024). "The association of the LPL variant with reduced susceptibility to CVD and type 2 diabetes could be mediated through the decrease in medium length TAGs." (PMID 31551469, 2019). "In this genetic association study including 392 220 people, triglyceride-lowering alleles in LPL or its inhibitor ANGPTL4 were associated with lower risk of coronary artery disease and type 2 diabetes in a consistent fashion across quantiles of the population distribution of LDL-C–lowering alleles." (PMID 30326043, 2018). "Moreover, an ATR1 antagonist, valsartan, increased blood LPL levels in type II diabetes with hypertension." (PMID 26447765, 2015). "The decrease in LPL activity seen in type 2 diabetes may be connected to this." (PMID 38303975, 2023). "However, the effects of PvuII polymorphisms of LPL on postprandial lipid profiles in response to a liquid high-fat meal have not been reported so far in type 2 diabetic patients with abdominal obesity." (PMID 28814963, 2017). "Drug target Mendelian randomization studies have demonstrated prospective evidence that the triglyceride-lowering alleles in the LPL pathway, which controls triglyceride hydrolysis, may be causally associated with lower risks of coronary heart disease and type 2 diabetes independent of LDL-C26,27." (PMID 38503751, 2024). "LPL mass and ApoC-III were the same but ANGPTL3 was lower in the group with type 2 diabetes compared with control participants." (PMID 37775612, 2023). "Original human studies in type 2 diabetes reporting cardiac metabolomics and LPL activity; no language restrictions." (PMID 41373652, 2025). "This study was specifically designed to test the hypothesis that the inclusion of NDGA, the functional role of which is to be an LPL inhibitor, exacerbates metabolic complications and alters HDL subclasses in the type-2 diabetes mice model, db/db mice." (PMID 31234537, 2019).
coronary artery disease (55 papers, 2006 to 2026). "Another example is LPL, which is negatively related to SED and considered to be protective for coronary artery disease, but some genetic variants of the LPL gene have been related to a higher risk of carotid stenosis." (PMID 40498722, 2025). "In a meta-analysis, the authors evaluated the association between rs268 and rs1801177 of the LpL gene and the risk for coronary heart disease." (PMID 38507115, 2024). "Previous studies have indicated that the LPL rs264 polymorphism is associated with an increased risk of coronary artery disease." (PMID 38392646, 2024). "On the other hand, heterozygous LPL-deficiency is associated with increased ischemic heart disease, elevated risk of coronary atherosclerosis and diminished clinical event–free survival." (PMID 32849290, 2020). "The LPL polymorphism contributed to the severity of coronary disease inpatients with MS and recent ACS." (PMID 29412239, 2018). "The association of LPL with lipid variables and coronary artery disease has been reported many times." (PMID 29410832, 2018). "The following key words were entered: “coronary artery disease”, “lipoprotein lipase” and “polymorphism”." (PMID 28275220, 2017). "It has been demonstrated that a reduced concentration of plasma LPL mass is associated with an increased risk of coronary artery disease." (PMID 27039080, 2016). "Evidence has been presented that gene polymorphisms (HindIII, PvuII and Ser447Ter) of lipoprotein lipase (LPL) are risk factors of coronary artery disease (CAD)." (PMID 22837712, 2012). "LPL has been extensively investigated as a potential risk factor for coronary artery disease." (PMID 33828969, 2021). "Similarly, QTLs for genes linked to coronary artery disease risk (e.g. LPL, SREBF1, GIT1, SKIV2L, MAP3K11/MLK3) were associated with colocalization sites linking coronary artery disease with mean platelet volume, lymphocyte, and/or reticulocyte counts." (PMID 32600345, 2020). "Furthermore, genetic variations in genes that play a role in lipid metabolism, including cholesteryl ester transfer protein, lipoprotein lipase, low-density lipoprotein receptor, and apolipoprotein E, have the potential to influence the risk of coronary artery disease." (PMID 39203810, 2024). "Potential physiological mechanisms linking sedentary behavior to higher FMI in patients with coronary artery disease include the suppression of lipoprotein lipase activity in skeletal muscles during prolonged sedentary periods, which favors fat accumulation." (PMID 41291462, 2025). "Human genetic studies have unequivocally demonstrated that activation of LPL pathway reduces risks for both coronary artery disease (CAD) and type 2 diabetes (T2D)." (PMID 40106311, 2025). "ANGPTL3 is an endothelial lipase inhibitor secreted from the liver that inhibits lipoprotein lipase, important for overall lipid metabolism, regulation, and coronary artery disease." (PMID 40924496, 2025). "Other evidence has also demonstrated that LPL genetic diversity plays a significant role in modulating serum HDL-c and TG levels, as well as the risk of ischemic heart disease." (PMID 37954769, 2023). "For example, rs1059611, significantly associated with increased HDL and decreased TG concentrations in patients with coronary heart disease, affects mRNA stability and LPL expression." (PMID 35241092, 2022). "In this regard, genetic studies have indicated that the LPL and APOC3 pathway is strongly associated with plasma TG as well as coronary artery disease, gathering a great deal of attention as a novel therapeutic target." (PMID 27039080, 2016). "Similar results were obtained in diabetic and coronary artery disease (CAD) patients carrying the PPARG 12Ala allele; plasma LPL activity was decreased in these patients." (PMID 25371663, 2014).